SARAF (store-operated calcium entry associated regulatory factor)
Description:
Negative regulator of store-operated Ca(2+) entry (SOCE) involved in protecting cells from Ca(2+) overfilling. In response to cytosolic Ca(2+) elevation after endoplasmic reticulum Ca(2+) refilling, promotes a slow inactivation of STIM (STIM1 or STIM2)- dependent SOCE activity: possibly act by facilitating the deoligomerization of STIM to efficiently turn off ORAI when the endoplasmic reticulum lumen is filled with the appropriate Ca(2+) levels, and thus preventing the overload of the cell with excessive Ca(2+) ions.
Synonyms: TMEM66; XTP3; HSPC035; MGC8721; FOAP-7
Tractability: Antibody: UniProt predicts a signal peptide or a membrane-spanning region. PROTAC: ubiquitination databases record sites on it; its protein half-life has been measured.
Gene: Protein-coding gene on chromosome 8 (30,063,003 to 30,083,208, reverse strand). Ensembl gene ENSG00000133872.
Subcellular location: Endoplasmic reticulum membrane; Endoplasmic reticulum membrane (Isoform 2)
Subcellular location (Human Protein Atlas): Endoplasmic reticulum; Rods & Rings
Gene Ontology:
Molecular function: protein binding
Biological process: regulation of store-operated calcium entry
Cellular component: endoplasmic reticulum; endoplasmic reticulum membrane; endoplasmic reticulum-plasma membrane contact site
Genetic constraint (gnomAD): Loss-of-function variants: 22 observed, 37.08 expected, observed/expected ratio (o/e) 0.59, 90% interval 0.42 to 0.85. The upper end of that interval is the gene's LOEUF score, 0.85, which puts it in group 3 of 6, group 1 being the genes least tolerant of losing a copy. Missense variants: 374 observed, 409.59 expected, observed/expected ratio (o/e) 0.91, 90% interval 0.84 to 1. Synonymous variants: 172 observed, 165.7 expected, observed/expected ratio (o/e) 1.04, 90% interval 0.92 to 1.18.
Homologues: Orthologues: chimpanzee SARAF (99% identical), macaque SARAF (98% identical), pig SARAF (84% identical), dog SARAF (83% identical), mouse Saraf (79% identical), rat Saraf (76% identical), rabbit SARAF (73% identical), guinea pig SARAF (63% identical), tropical clawed frog saraf (43% identical), zebrafish saraf (40% identical), Caenorhabditis elegans T06D8.9 (33% identical).
Diseases named in the same sentence as SARAF in open-access papers:
SARAF is named in the same sentence as 16 diseases in open-access papers, as found by Europe PMC text mining. Sharing a sentence is not in itself a finding about the gene and the disease. The quoted sentences say what the papers report.
cardiac hypertrophy (4 papers, 2020 to 2021). "It is also of interest that another ER-resident protein, SOCE-associated regulatory factor (SARAF), when overexpressed, can mitigate the effect of STIM1 in cardiac hypertrophy and diastolic dysfunction." (PMID 32330125, 2020). "Indeed, consistent with the results of our study, a very recent study on mice with cardiac hypertrophy showed that higher Ca2+ levels induced by aberrant Ca2+ entry by overexpression of SARAF, a negative regulator of SOCE, promotes hypertrophy at least in part through mTORC1 hyperactivation." (PMID 34198993, 2021). "In addition, a knock-down in the expression level of SARAF yet concomitant increases in these of Orai1 and STIM1 have recently been shown to correlate with cardiac hypertrophy, the latter of which was attenuated upon overexpressing SARAF in a mouse model system." (PMID 33466526, 2021).
acute pancreatitis (3 papers, 2021 to 2025). An acute inflammatory process that leads to necrosis of the pancreatic parenchyma. "While under physiological conditions, SOCE-associated regulatory factor (SARAF) terminates Orai1 activity once refilling is complete, and its downregulation in acute pancreatitis amplifies Ca2+ influx and tissue injury." (PMID 41470786, 2025). "Recent studies demonstrated that galactose and channel inactivator store-operated calcium entry-associated regulatory factor (SARAF) play a role in preventing pancreatic damage during development of acute pancreatitis." (PMID 33806041, 2021).
breast carcinoma (3 papers, 2021 to 2025). "Here, we determined the effect of the cytoplasmic C-terminal region of SARAF on the SOCE response in breast cancer and in the critical cellular events leading to the malignant phenotype, such as tumor cell proliferation, motility, and metastasis." (PMID 36982380, 2023). "Using both in vitro and in vivo approaches, we showed that overexpression of the C-terminal SARAF fragment reduced proliferation, cell migration, and the invasion of murine and human breast cancer cells by decreasing the SOCE response." (PMID 36982380, 2023). "As a decrease in SOCE response affects malignancy of breast cancer cells, we generated a C-terminal fragment of SARAF fused to mScarlet fluorescent protein (mScarlet-C-SARAF) and evaluated the effect of its overexpression on the SOCE response." (PMID 36982380, 2023). "By contrast, our results indicate that SARAF plays a positive role in SOCE in ER+ breast cancer cells." (PMID 34439314, 2021). "Our findings reveal that SARAF knockdown significantly reduces SOCE in the ER+ breast cancer MCF7 cell line." (PMID 34439314, 2021). "SARAF expression was found to be similar in breast cancer and pre-neoplastic breast epithelial cells, and SARAF knockdown was found to result in enhanced SOCE in pre-neoplastic and TNBC cells." (PMID 34439314, 2021). "Beyond liver cancer, it is important to assess whether SARAF’s potential tumor-suppressive function is conserved in other malignancies characterized by dysregulated calcium signaling, such as breast cancer and colorectal cancer." (PMID 40362663, 2025). "To evaluate whether canonical SOCE components including the Orai1, STIM1, and SARAF proteins, are correlated with breast cancer metastatic potential, we consulted The Cancer Genome Atlas Program (TCGA) NIH database using the GEPIA platform." (PMID 36982380, 2023). "However, while the expression of SARAF is similar in breast cancer and pre-neoplastic cells, EFHB expression is significantly greater in cancer cells." (PMID 34439314, 2021). "Our results further indicate that EFHB and SARAF are required for breast cancer MCF7 and MDA-MB-231 cells viability, proliferation, and migration, although the signaling pathway might differ between both cell types." (PMID 34439314, 2021). "Here, we show that the expression and/or function of SARAF and EFHB is altered in breast cancer cells and both proteins are required for cell proliferation, migration, and viability." (PMID 34439314, 2021). "Our results indicate that SARAF and EFHB are expressed in breast cancer and pre-neoplastic breast epithelial cells and play a relevant role in SOCE." (PMID 34439314, 2021). "In aggregate, SARAF and EFHB are required for the fine modulation of SOCE in breast cancer cells and play an important role in the maintenance of proliferation, migration, and viability in these cells." (PMID 34439314, 2021). "Here, we show that SARAF and EFHB are expressed in neoplastic and pre-neoplastic breast cells, with breast cancer cells showing upregulation of EFHB expression." (PMID 34439314, 2021). "Cell viability, proliferation, and migration is strongly dependent on SARAF and EFHB, or exclusively SARAF, in breast cancer and pre-neoplastic cells, respectively, thus suggesting that these proteins play an important role in breast cancer development and progression." (PMID 34439314, 2021). "Finally, we used a combination of approaches to show that molecular knockdown of SARAF and EFHB significantly attenuates the ability of breast cancer cells to proliferate and migrate, as well as cell viability." (PMID 34439314, 2021). "While SARAF expression is similar in neoplastic and pre-neoplastic cells, EFHB is overexpressed in breast cancer cells, which might partially explain the enhanced SOCE observed in cancer cells." (PMID 34439314, 2021).
pancreatitis (3 papers, 2021 to 2025). Inflammation of the pancreas. "Mice in which the SARAF gene had been knocked out developed more pronounced pancreatitis, whereas overexpression of SARAF suppressed inflammation and dampened pancreatitis." (PMID 40459545, 2025).
multiple sclerosis (2 papers, 2023 to 2025). A progressive autoimmune disorder affecting the central nervous system resulting in demyelination. "This study provides convincing evidence for the involvement of Store-Operated Calcium Entry-Associated Regulatory Factor (SARAF) in the pathophysiology of Multiple Sclerosis (MS)." (PMID 40429665, 2025). "In the later study, the authors also pointed to particular Middle East and Gulf region populations and stated that further studies are required in order to elucidate the role of the SARAF gene in multiple sclerosis, depicting an awareness of genetic heterogeneity between different populations." (PMID 37372417, 2023).
neuroblastoma (2 papers, 2020 to 2021). Neuroblastoma (NB) is the most common solid, extracranial childhood tumor. "The overexpression of SARAF in neuroblastoma cells attenuated the arachidonic acid (AA)-induced Ca2+ response, and the transfection of SARAF siRNA enhanced AA-stimulated Ca2+ influx via ARC channels." (PMID 33424550, 2020).
colon cancer (1 paper, 2023). "Accordingly, both technologies reported the overexpression of STIM1, MBP, SEPTIN9, and SEPTIN10 and the downregulation of CRACR2A, ORMDL3, SARAF, SEPTIN3, and SEPTIN6 in colon cancer cells." (PMID 36900391, 2023).
liver cancer (1 paper, 2025). An epithelial or non-epithelial malignant neoplasm that arises from the liver. "The observed effects of SARAF silencing and overexpression on the proliferation of HepG2 liver cancer cells highlight the critical role of SARAF in cellular growth regulation." (PMID 40362663, 2025). "In conclusion, this preliminary study identified SARAF as a potential tumor suppressor and regulator of calcium homeostasis in liver cancer." (PMID 40362663, 2025). "Overall, the data presented in the image suggest that the SARAF gene is expressed at a relatively high level in liver cancer samples, which could be an important factor in the molecular mechanisms underlying liver carcinogenesis." (PMID 40362663, 2025). "The results suggest that targeting SARAF-mediated calcium signaling pathways could be a potential therapeutic strategy for liver cancer treatment." (PMID 40362663, 2025). "This suggests that silencing the SARAF gene leads to an increase in the proliferation of HepG2 liver cancer cells and SARAF may play a role in regulating the proliferation of these cancer cells." (PMID 40362663, 2025). "The high levels of SARAF in liver tissue and its possible role in affecting Ca2+ signaling imply that targeting SARAF could help slow liver cancer growth." (PMID 40362663, 2025). "While SARAF has been implicated in calcium signaling regulation, particularly through its role in modulatingSOCE, its potential tumor-suppressive function in liver cancer has not been previously explored." (PMID 40362663, 2025).
Stormorken syndrome (1 paper, 2021). Stormorken-Sjaastad-Langslet syndrome is characterized by thrombocytopathy, asplenia, miosis, muscle fatigue, migraine, dyslexia, and ichthyosis. "Whether changes in SARAF expression or loss-of-function mutations in SARAF are associated with Stormorken syndrome is currently unknown but presents an interesting avenue to explore." (PMID 34440656, 2021).
Stroke (1 paper, 2020). Sudden impairment of blood flow to a part of the brain due to occlusion or rupture of an artery to the brain. "Notably, a recent study reported a reduction of the expression of STIM1 and SARAF in the ischemic cortex, indicating that SARAF may be a new neuroprotective target for the treatment of stroke." (PMID 33424550, 2020).
triple-negative breast carcinoma (1 paper, 2021). An invasive breast carcinoma which is negative for expression of estrogen receptor (ER), progesterone receptor (PR), and human epidermal growth factor receptor 2 (HER2). "In the present study, we have investigated the role of SARAF and EFHB in SOCE in ER+ and triple negative breast cancer (TNBC) cells." (PMID 34439314, 2021).
cancer (5 papers, 2021 to 2025). A tumor composed of atypical neoplastic, often pleomorphic cells that invade other tissues. "The reduction in calcium levels observed from SARAF overexpression suggests a potential therapeutic role for SARAF in modulating calcium homeostasis in cancer cells." (PMID 40362663, 2025). "Store-operated calcium entry (SOCE), involving components such as STIM1, Orai1, and SARAF, plays a critical role in calcium signaling and cancer progression." (PMID 40362663, 2025). "Additionally, SARAF overexpression partially restored calcium homeostasis by reducing the elevated intracellular calcium levels characteristic of cancer cells." (PMID 40362663, 2025). "There are plenty of regulatory proteins, including CRACR2A, SEPTIN4, STIMATE, GOLLI, SARAF, ORMDL3 and so on, that contribute to alter SOCE activity in cancer, immune diseases and inflammation disorders." (PMID 36128650, 2022). "For instance, SARAF may influence epithelial-to-mesenchymal transition (EMT), a key process in cancer metastasis that is regulated by calcium signaling." (PMID 40362663, 2025). "Furthermore, we have evaluated the role of SARAF in SOCE in MCF10A cells and the cancer cell lines MCF7 and MDA-MB-231." (PMID 34439314, 2021). "Interestingly, it has been demonstrated that SARAF and Orai1 work together to boost SOCE in highly proliferated cancers cells, MEG01 and NG115-401L, independently of STIM1." (PMID 33748129, 2021). "Silencing SARAF via siRNA did not result in any significant changes compared to the control group, suggesting that SARAF knockdown does not further influence the already dysregulated calcium signaling typical of cancer cells." (PMID 40362663, 2025).
tumor (4 papers, 2023 to 2025). "This preliminary study provided initial insights into SARAF as a potential regulator of tumor suppression and calcium homeostasis in hepatocellular carcinoma (HCC)." (PMID 40362663, 2025). "This study identified SARAF as a potential regulator of tumor suppression and calcium homeostasis in hepatocellular carcinoma (HCC)." (PMID 40362663, 2025). "Our findings also suggested that SARAF’s possible tumor-suppressive effects extend beyond calcium regulation." (PMID 40362663, 2025). "In this study, SARAF silencing significantly increased HepG2 cell proliferation, suggesting that SARAF may function as a tumor suppressor by limiting calcium influx and thereby controlling excessive cell growth." (PMID 40362663, 2025). "Functional assays demonstrated that SARAF silencing increased proliferation by 50% and migration by 40% (p < 0.05), while SARAF overexpression reduced proliferation by 50% and migration by 45% (p < 0.01), highlighting its tumor-suppressive role." (PMID 40362663, 2025). "Therefore, since triple-negative tumors have high metastatic potential compared to other tumors, decreased SARAF expression can be correlated to a higher migration and invasive tumor phenotype." (PMID 36982380, 2023). "SARAF’s ability to inhibit SOCE and restore calcium balance provides a novel mechanism by which it may suppress tumor growth and invasion." (PMID 40362663, 2025).
SARAF also shares sentences with these, for which no sentence is quoted: colorectal cancer (1 paper); immune diseases (1); Sézary syndrome (1).